TWIST1 (twist family bHLH transcription factor 1)
Diseases named in the same sentence as TWIST1 in open-access papers (continued):
Sharing a sentence is not in itself a finding about the gene and the disease.
vascular disorder (1 paper, 2021). A general term used to describe any disease affecting blood vessels]. "Despite human studies and functional animal experiments have suggested the potential participation of TWIST1 in vascular disorders, little information is presently available regarding its role in SMC homeostasis." (PMID 33470057, 2021). "Notably, recent reports have suggested a potential role of TWIST1 in the pathogenesis of vascular disorders." (PMID 33470057, 2021). "TWIST1 might be a potential therapeutic target in phenotype‐related vascular disorders." (PMID 33470057, 2021). "Therefore, TWIST1 might be a attractive therapeutic target for inhibiting phenotype‐related vascular disorders." (PMID 33470057, 2021).
TWIST1 also shares sentences with these, for which no sentence is quoted: breast (8 papers); lymph node (5); Apert syndrome (3); craniosynostosis syndrome (3); kidney cancer (3); liver diseases (3); periodontitis (3); thyroid (3); anaplastic large cell lymphoma (2); blood cancer (2); chronic obstructive pulmonary disease (2); cutaneous T-cell lymphoma (2); hemangioblastoma (2); hemangiopericytoma (2); Hematuria (2); IgA nephropathy (2); Intellectual disability (2); laryngeal carcinoma (2); liver cirrhosis (2); malignant pleural mesothelioma (2); metastatic prostate carcinoma (2); Mycosis (2); papillary carcinoma (2); pharyngeal squamous cell carcinoma (2); preeclampsia (2); synovial sarcoma (2); T-cell lymphoma (2); thyroid tumor (2); type 2 diabetes (2); ulcerative colitis (2).
A further 111 diseases each share a sentence with TWIST1 in 1 paper.